GBP1 (guanylate binding protein 1)
Diseases named in the same sentence as GBP1 in open-access papers (continued):
Sharing a sentence is not in itself a finding about the gene and the disease.
lung adenocarcinoma (7 papers, 2020 to 2026). A carcinoma that arises from the lung and is characterized by the presence of malignant glandular epithelial cells. "Our previous study constructed a risk model developed based on eight genes, including GBP1, to predict prognosis and associate with tumor immunity of patients with lung adenocarcinoma (LUAD)." (PMID 35222540, 2022). "RT-PCR demonstrated that the strongest expression of GBP1 in lung adenocarcinoma cell lines was observed in NCI-H820, followed by A549, whereas the gene expression for GBP1 was lower in PC-9 and NCI-H441." (PMID 40018406, 2025). "In lung adenocarcinoma, GBP1 boosts cell motility and invasiveness by binding beta-tubulin, increasing metastatic potential to distant sites such as lymph nodes, bones, or the brain, a process linked to its plasma membrane localization and GTPase activity." (PMID 40564939, 2025). "GBP1 gene and protein expressions were confirmed in several human lung adenocarcinoma cell lines, and differences in relative expression levels were observed between these cell lines." (PMID 40018406, 2025). "Although GPB1 promotes malignant progression in both types of adenocarcinoma, the specific role of GBP1 differs depending on the stage of malignant progression of lung adenocarcinoma." (PMID 40018406, 2025). "Nevertheless, based on the results of the in vitro experiments in this study, GBP1 plays a crucial role in the malignant progression of lung adenocarcinoma." (PMID 40018406, 2025). "GBP1 enhances lung adenocarcinoma invasiveness by binding beta-tubulin, increasing cell motility, and enabling metastatic dissemination to distant organs like lymph nodes, bones, or brain, driven by its GTPase activity and plasma membrane localization." (PMID 40564939, 2025). "First, the lack of in vivo experiments or research results introduces uncertainty regarding the validity of GBP1 as a potential target for treating human lung adenocarcinoma." (PMID 40018406, 2025). "Guanylate-binding protein 1 (GBP1) is involved in the malignant progression of lung adenocarcinoma, particularly in the acquisition of invasive potential." (PMID 40018406, 2025). "Further studies are necessary to validate the results of this study and expand the indications of GBP1 inhibitors as human therapeutics for lung adenocarcinoma." (PMID 40018406, 2025). "GBP1 is a prognostic factor that may be involved in the proliferation of invasive lung adenocarcinoma, suggesting that inhibiting GBP1 activity may be a promising therapeutic approach for lung adenocarcinoma patients expressing GBP1." (PMID 40018406, 2025). "In addition, GBP1 expression was detected in resected specimens from patients with lung adenocarcinoma using immunohistochemistry, and GBP1 positivity was correlated with lymphatic vessel invasion." (PMID 40018406, 2025). "Furthermore, GBP1 promotes the migratory ability of non-invasive lung adenocarcinoma cells, indicating its potential role in invasion." (PMID 40018406, 2025). "Furthermore, using inhibitors targeting GBP1 in human lung adenocarcinoma cell lines, the role of GBP1 on invasive adenocarcinoma cell proliferation was evaluated." (PMID 40018406, 2025). "Although the role of GBP1 in the malignant progression of non-invasive lung adenocarcinoma cells have been documented, the expression status of GBP1 and its role in invasive adenocarcinoma remain unclear." (PMID 40018406, 2025). "Therefore, inhibiting the activity of GBP1 may be a promising therapeutic approach for patients with lung adenocarcinomas expressing GBP1." (PMID 40018406, 2025). "In conclusion, GBP1 may be involved in the proliferation of invasive lung adenocarcinomas." (PMID 40018406, 2025). "Approximately 50% of the lung adenocarcinomas without non-invasive components were positive for GBP1, in contrast to previous findings that demonstrated that only 12.5% of the tumors were positive in patients with lung adenocarcinomas containing non-invasive components." (PMID 40018406, 2025).
lung adenocarcinoma (continued). "Additionally, the possibility of targeting GBP1 for treating GBP1-positive lung adenocarcinoma cells has not been elucidated." (PMID 40018406, 2025). "Additionally, the expression levels of GBP1 gene and protein levels were evaluated in lung adenocarcinoma cell lines (PC-9, A549, NCI-H322, NCI-H441, NCI-H820, and ABC-1), and its proliferative role in these cell lines was analyzed using specific inhibitors targeting GBP1." (PMID 40018406, 2025).
lung carcinoma (7 papers, 2019 to 2025). "In lung cancer, elevated GBP1 is linked to erlotinib resistance, serving as a prognostic warning for EGFR-targeted therapies and detectable via quantitative PCR (qPCR), proteomic assays, or circulating tumor DNA analysis." (PMID 40564939, 2025). "Knocking down GBP1 restores erlotinib sensitivity in lung cancer, shrinking tumors and prolonging G1 phase arrest, trackable via cell cycle analysis, positron emission tomography (PET) imaging, or tumor biopsies, offering a dynamic response marker." (PMID 40564939, 2025). "Interferon-induced guanylate-binding protein 1 (GBP1)-mediated extracellular secretion of IDO1 stimulates the progression of lung cancer cells." (PMID 34201791, 2021). "In vitro study showed that the high expression levels of IDO1 and GBP1 in lung cancer cells promoted cell invasion and migration." (PMID 33552086, 2020). "In order to verify the role of IDO1 and GBP1 in lung cancer species, western blot was performed to detect the expression levels of IDO1 and GBP1 in 6 lung cancer cell lines." (PMID 33552086, 2020). "This study showed that IDO1 can bind to GBP1 and increase the extracellular secretion of IDO1 with the assistance of GBP1, thereby promoting the malignant proliferation and metastasis of lung cancer." (PMID 33552086, 2020). "Then the effects of IDO1 and GBP1 on the invasion, migration and colony formation ability of lung cancer cells were tested by transwell, wound healing and colony formation assay." (PMID 33552086, 2020). "This indicated that inhibiting the extracellular secretion of IDO1 by blocking the interaction of IDO1 and GBP1 can also inhibit the malignant progression of lung cancer cells." (PMID 33552086, 2020). "In vivo and in vitro experiments showed that the simultaneous overexpression of IDO1 and GBP1 can promote the migration and invasion of lung cancer cells." (PMID 33552086, 2020). "Astragaloside IV can block the combination of IDO1 and GBP1 to prevent the exhaustion of T cells caused by the extracellular secretion of IDO1, and further enhance the inhibitory effect of PD-1 inhibitors in lung cancer." (PMID 33552086, 2020). "Preclinical success with GBP1 knockdown in lung cancer suggests translational potential, but scaling to humans requires overcoming pharmacokinetic hurdles (e.g., half-life, bioavailability), safety concerns (e.g., immunogenicity), and clinical trial design, assessable through phase I/II studies." (PMID 40564939, 2025). "In addition, astragaloside IV can block the combination of IDO1 and GBP1 to inhibit the progression of lung cancer." (PMID 33552086, 2020). "In tail vein mice, knocking down IDO1 and GBP1 can inhibit the metastasis of lung cancer cells." (PMID 33552086, 2020). "In order to verify the precise mechanism of GBP1 and IDO1 interaction and its role in lung cancer cells, we simulated the interaction between GBP1 and IDO1 using molecular docking." (PMID 33552086, 2020). "The interaction of GBP1 and IDO1 induced the extracellular secretion of IDO1 promote lung cancer cell progression." (PMID 33552086, 2020). "In addition, astragaloside IV can block the interaction between GBP1 and IDO1 and enhance the inhibitory effect of PD-1 inhibitors of lung cancer cell in vivo and in vitro." (PMID 33552086, 2020). "These experiments indicated that IDO1 and GBP1 contributed to the malignant progression of lung cancer, which may due to the interaction between IDO1 and GBP1." (PMID 33552086, 2020).
skin cutaneous melanoma (6 papers, 2020 to 2024). "Moreover, higher GBP1-6 expression is associated with better OS in skin cutaneous melanoma patients." (PMID 34439200, 2021). "High expression of GBP1-5 has been correlated with favorable overall survival in skin cutaneous melanoma (SKCM) patients." (PMID 39114443, 2024). "Besides, the GBP1 expression was significantly upregulated in metastasis samples of skin cutaneous melanoma (SKCM) versus primary tumor samples (p < 0.001)." (PMID 35222540, 2022).
cervical cancer (5 papers, 2021 to 2025). A primary or metastatic malignant neoplasm involving the cervix. "The prognostic analysis of 104 cases of cervical cancer showed that high GBP1 level on tumor cells was associated with poor prognosis of cervical cancer patients." (PMID 38167153, 2024). "Result showed that a higher proportion of GBP1+ cervical cancer cells to cervical cancer cells was associated with poorer OS." (PMID 38167153, 2024). "For the first time, we had linked GBP1 to cancer-promoting effects in cervical cancer." (PMID 38167153, 2024). "In cervical cancer, GBP1, after binding to HNRNPK, regulates CD44 protein expression through alternative splicing at the 3′ splice site, ultimately playing a cancer-promoting role." (PMID 40018406, 2025). "GBP1 overexpression can promote the proliferation and invasion of cervical cancer cells and promote tumor growth." (PMID 38167153, 2024). "In this study, we first found that GBP1 was generally expressed in cervical cancer in various online databases and was closely related to immune invasion." (PMID 38167153, 2024). "In other words, this showed that the number of GBP1-positive cervical cancer cells in cervical cancer cells had a certain impact on the survival of cervical cancer patients." (PMID 38167153, 2024). "In this study, we first found that GBP1 was widely present in a variety of tumor tissues and immune cells, including cervical cancer tissues." (PMID 38167153, 2024). "In summary, to the best of our knowledge, this study was the first to examine in depth the effects of GBP1 in cervical cancer." (PMID 38167153, 2024). "In order to explore the influence and mechanism of GBP1 on the occurrence and progression of cervical cancer, we analyzed the correlation between GBP1 and PD-1 and PD-L1 in cervical cancer tissues by multicolor immunofluorescence staining." (PMID 38167153, 2024). "This study focused on the important role of GBP1 in tumor immunity, its cancer-promoting effect on cervical cancer and its mechanism." (PMID 38167153, 2024). "We found that the expression of GBP1 on TILs was strongly correlated with the expression of PD-1 and PD-L1, and the expression of GBP1 on cervical cancer cells was strongly correlated with the expression of PD-L1." (PMID 38167153, 2024). "We aim to explore the effects of GBP1 on cervical cancer through bioinformatics and related experiments." (PMID 38167153, 2024). "The percentage of CK+GBP1+ cells was strongly positively correlated with the percentage of CK+PD-L1+ cells, indicating that the expression of GBP1 on the surface of cervical cancer cells was strongly correlated with the expression of PD-L1." (PMID 38167153, 2024). "Knockdown and overexpression assays of GBP1 in vitro were used to prove GBP1 as a potential oncogene of cervical cancer, and its carcinogenicity was verified by in vivo experiment." (PMID 38167153, 2024). "At the same time, we found that the high expression of GBP1 in cervical cancer was related to drug sensitivity such as Cediranib, BLU-667, JNJ-42756493 and Pazopanib, which is manifested as treatment resistance." (PMID 38167153, 2024). "Secondly, we used multicolor immunofluorescence technology to verify the expression of GBP1 in cervical cancer tissues and its relationship with immune invasion, and explored its relationship with the prognosis of patients with cervical cancer." (PMID 38167153, 2024). "LINC01783 has been identified as an oncogene in the process of cervical cancer through targeting miR-199b-5p/GBP1." (PMID 33902591, 2021). "In 2020, the promoting role of LINC01783 in cervical cancer via regulating miR-199b-5p/GBP1 has been verified." (PMID 33902591, 2021). "In addition, we found that the expression of GBP1 on cervical cancer cells was also correlated with the expression of PD-1 and PD-L1 on TILs." (PMID 38167153, 2024). "At present, there are rare reports on the role of GBP1 in cervical cancer." (PMID 38167153, 2024).
cervical cancer (continued). "It has been reported that the expression of GBP1 in cervical cancer was significantly higher than that in normal cervical tissues (p < 0.01), but whether GBP1 has anti-HPV effect and the related mechanism remain to be studied." (PMID 38622605, 2024). "We found that GBP1 silencing could inhibit the proliferation and invasion of cervical cancer cells and promote the apoptosis of tumor cells." (PMID 38167153, 2024). "In this study, the bioinformatics methods combined with a large number of in vitro and in vivo experiments were used to fully elucidate the potential biological functions of GBP1 in cervical cancer and conduct in-depth research on its cancer-promoting mechanism." (PMID 38167153, 2024). "Meanwhile, we found that GBP1 overexpression could promote the proliferation and invasion of cervical cancer cells, and GBP1 overexpression could promote tumor growth in cervical cancer." (PMID 38167153, 2024). "In order to verify whether CK+GBP1+/CK+ (%) is an independent factor affecting the prognosis of patients with cervical cancer, univariate and multivariate Cox analyses were subsequently performed." (PMID 38167153, 2024). "This will lay a foundation for GBP1 as a new therapeutic target for cervical cancer." (PMID 38167153, 2024). "In addition, we cross-analyzed the correlation between GBP1 on cervical cancer cells and PD-1 and PD-L1 on TILs, and the results showed that there was also a certain correlation." (PMID 38167153, 2024). "Therefore, we believe that GBP1 has a cancer-promoting effect in cervical cancer." (PMID 38167153, 2024). "Similarly, our study found that GBP1 played an important role in tumor immunity in cervical cancer." (PMID 38167153, 2024). "We detected the expression of GBP1, CD3, PD-1, PD-L1 and CK by polychromatic immunofluorescence staining in 104 cases of cervical cancer." (PMID 38167153, 2024). "That is, GBP1, after binding with HNRNPK, regulates the expression of CD44 protein through A3SS alternative splicing form, and finally plays a cancer-promoting role in cervical cancer." (PMID 38167153, 2024). "Using the single-cell sequencing data of cervical cancer samples (E-MTAB-11948), UAMP dimensional reduction analysis was performed on 3 patients with cervical cancer expressing GBP1, and the results showed that GBP1 was expressed in cells such as fibroblasts, T cells and neutrophils." (PMID 38167153, 2024). "However, there was no statistical difference in the percentage of CK+GBP1+ cells between early cervical cancer and advanced cervical cancer tissues." (PMID 38167153, 2024). "Combined with the existing reports and the results of RNA-seq alternative splicing analysis, it is speculated that GBP1 may regulate the alternative splicing of CD44 protein by binding to interacting protein-HNRNPK, and thus play a role in promoting cancer in cervical cancer." (PMID 38167153, 2024). "Combined with the existing reports and GBP1-regulated AS events, we finally obtained a regulatory pathway, that is, GBP1 and HNRNPK binding, through the A3SS alternative splicing form, regulate the expression of CD44 protein, and finally play a cancer-promoting role in cervical cancer." (PMID 38167153, 2024).
oral squamous cell carcinoma (5 papers, 2016 to 2025). "In contrast, GBP1 is upregulated and a poor prognostic marker in oral cavity squamous cell carcinoma (OSCC)." (PMID 26848767, 2016). "GBP1 regulates migration and invasion of oral squamous cell carcinoma in vitro." (PMID 40018406, 2025).
osteosarcoma (5 papers, 2021 to 2025). A usually aggressive malignant bone-forming mesenchymal neoplasm, predominantly affecting adolescents and young adults. "Transwell assays further revealed that GBP1 silencing impaired, whereas GBP1 overexpression promoted, migration and invasion of osteosarcoma cells." (PMID 40975978, 2025). "Using the GEPIA platform, we identified a positive correlation between GBP1 and PD-L1 expression in sarcoma tissues, a finding further supported by IHC analysis in osteosarcoma tissues." (PMID 40975978, 2025). "Here, we demonstrate that differential expression of GBP1 significantly influences PD-L1 expression and mediates immune escape in osteosarcoma." (PMID 40975978, 2025). "In this study, we observed a positive correlation between GBP1 and PD-L1 expression at both mRNA and protein levels in osteosarcoma tissues." (PMID 40975978, 2025). "In this study, we found that GBP1 influences the tumor immune environment of osteosarcoma by modulating PD-L1 transcription and translation." (PMID 40975978, 2025). "An examination of multiple public databases revealed an upregulation of GBP1 in various tumors, including osteosarcoma." (PMID 37796192, 2023). "The results showed that 79 DEGs affected the prognosis of osteosarcoma, with PDE4C, CFAP44, CARNS1, GREB1L, ROF207 identified as significant risk factors and GBP1, MSC, GBP3, F13A1, CCL2 as substantial protective factors." (PMID 37796192, 2023). "The results showed a significant increase in GBP1 expression levels in osteosarcoma cells compared to osteoblasts." (PMID 37796192, 2023). "Analysis of the GSE225588 and GSE99671 datasets revealed a considerable upregulation of GBP1 expression in osteosarcoma samples." (PMID 37796192, 2023). "In line with recent research findings and our results, GBP1 seems to act as a protective factor in osteosarcoma." (PMID 37796192, 2023). "GBP1 knockdown by siRNA markedly reduced its expression in osteosarcoma cells." (PMID 40975978, 2025). "Additionally, IHC staining with a GBP1-specific antibody confirmed the upregulation of GBP1 in stage 2 osteosarcoma tissues, in parallel with PD-L1 expression." (PMID 40975978, 2025). "Furthermore, the quantification of GBP1 expression was performed in both osteosarcoma and osteoblasts cell lines." (PMID 37796192, 2023). "Finally, GBP1, a gene highly expressed in osteosarcoma, was identified as a potential prognostic biomarker with promising implications." (PMID 37796192, 2023). "RT-qPCR further confirmed high GBP1 expression in osteosarcoma cell lines." (PMID 37796192, 2023). "Finally, GBP1, a potential biomarker with high expression in osteosarcoma was identified." (PMID 37796192, 2023). "Co-immunoprecipitation confirmed that CDK9 interacts with both GBP1 and STAT3 in osteosarcoma cells." (PMID 40975978, 2025). "Combining literature reports and our results of bioinformatics and RT-qPCR, we hold that EPHX2 and FDPS are the oncogenes, while GBP1, MMD and ZYX are the anti-oncogene in osteosarcoma." (PMID 37090691, 2023).
sarcoidosis (5 papers, 2013 to 2025). Sarcoidosis is a multisystemic disorder of unknown cause characterized by the formation of immune granulomas in involved organs. "Compared to HCs, serum from patients with sarcoidosis significantly (p < 0.05) induced the expression of FCGR1B and IFIT2, whereas serum from patients with TB significantly (p < 0.05) reduced the expression of GBP1, SERPING1, and UBE2L6 compared to HCs." (PMID 39309852, 2024). "The induced expression levels of the individual genes FCGR1B, GBP1, IFIT2, SERPING1, and UBE2L6 could discriminate between patients with sarcoidosis and TB with a maximum Youden's index >0.80 and corresponding sensitivity >88 % and specificity >89 %." (PMID 39309852, 2024).